SULF1 (sulfatase 1)
Diseases named in the same sentence as SULF1 in open-access papers (continued):
Sharing a sentence is not in itself a finding about the gene and the disease.
head and neck squamous cell carcinoma (4 papers, 2015 to 2025). A squamous cell carcinoma that arises from any of the following anatomic sites: lip and oral cavity, nasal cavity, paranasal sinuses, pharynx, larynx, and salivary glands. "Analysis of a single-cell RNA-seq (scRNA-seq) dataset of head and neck squamous cell carcinoma (HNSC) showed the highest positivity of SULF1 in fibroblasts." (PMID 41373732, 2025).
lung carcinoma (4 papers, 2012 to 2024). "The levels of PSAP and SULF-1 were measured in PE of MPM and control (lung cancer and benign pleural disease) patients by enzyme-linked immunosorbent assay (ELISA)." (PMID 36359323, 2022). "Pleural effusions from a total of 44 patients (23 with mesothelioma, 8 with lung cancer, and 13 with non-malignant disease) were analyzed for prosaposin and SULF-1 by enzyme-linked immunosorbent assay." (PMID 36359323, 2022).
lymph node metastasis (4 papers, 2014 to 2024). "In the context of GC, it has been documented that the presence of SULF1 is correlated with an unfavorable prognosis and an increased risk of lymph node metastases, while several researchers demonstrated that SULF1 inhibited GC cells proliferation and invasion." (PMID 38438372, 2024). "As for GC, SULF1 has been reported to be associated with poor prognosis and lymph node metastasis." (PMID 38438372, 2024). "Multivariate analysis revealed that Sulf1 is an independent prognostic factor and lymph node metastasis predictive factor in these patients." (PMID 25105093, 2014).
bladder cancer (3 papers, 2021 to 2025). "In this study, we identified six ECM-related genes (CTHRC1, MMP11, COL10A1, FSTL1, SULF1, and COL5A3) that were associated with bladder cancer occurrence, tumor stage, and prognosis based on the bladder cancer tumor samples." (PMID 35450397, 2022). "Based on the TCGA dataset, the expression levels of COL10A1, COL5A3, CTHRC1, MMP11, and SULF1 in the bladder cancer tissues were higher than those in the normal bladder tissues." (PMID 35450397, 2022). "While, some other studies have shown up-regulation of SULF1 expression in gastric, colorectal and bladder cancer." (PMID 34107956, 2021). "SULF1 is one of the regulators of the constituent molecules of the ECM, and upregulation of SULF1 is linked to tumor progression and a negative prognosis for bladder cancer." (PMID 35450397, 2022).
chondrosarcoma (3 papers, 2023 to 2024). A malignant cartilaginous matrix-producing mesenchymal neoplasm arising from the bone and soft tissue. "We also tested whether the loss of EZH2, which induces SULF1 expression, would impair cMET phosphorylation in chondrosarcoma cell lines." (PMID 36622753, 2023). "The downregulation of SULF1 promoted the malignancy of chondrosarcoma by regulating the receptor tyrosine kinase signaling." (PMID 38438372, 2024). "The ectopic expressed SULF1 of chondrosarcoma cell lines showed the cell surface staining for N-sulfated glucosamine containing HSGAGs was diminished compared with vector control chondrosarcoma cell lines via using flow cytometry analysis." (PMID 36622753, 2023). "We demonstrated that EZH2/SULF1 axis mediates cMET in chondrosarcoma, and inhibition of cMET at low dose for long-term administration effectively alleviates tumor growth of chondrosarcoma and prolongs survival in mice." (PMID 36622753, 2023). "A non-biased chromatin immunoprecipitation sequence, cDNA microarray analysis, and validation of chondrosarcoma cell lines identified sulfatase 1 (SULF1) as the top EZH2-targeted gene to regulate chondrosarcoma progression." (PMID 36622753, 2023). "SULF1 ectopic-expression inhibited chondrosarcoma cell proliferation, migration, and colony-forming capacity." (PMID 36622753, 2023). "Overexpressed EZH2 resulted in downregulation of SULF1 in chondrosarcoma cell lines, which in turn activated cMET pathway." (PMID 36622753, 2023). "Consistently, qRT-PCR analysis showed that SULF1 was downregulated in chondrosarcoma cell lines, JJ012 and CH2879 as compared with normal chondrocyte." (PMID 36622753, 2023). "We also examined the role of SULF1 in chondrosarcoma growth using an alternative tumor xenograft model." (PMID 36622753, 2023). "It is worth to mention that the SULF1 level in the transfected chondrosarcoma cell lines are comparable to the expression level of SULF1 in primary normal chondrocytes (n=107) by using qRT-PCR analysis." (PMID 36622753, 2023). "We unravel the critical roles of SULF1 in suppressing tumor growth of chondrosarcoma by reducing RTK signaling pathway such as cMET which is known to increase malignancy and causes resistance to target therapy." (PMID 36622753, 2023). "Targeting EZH2/SULF1/cMET shown in this report provides proof of concept evidence to use cMET as biomarker to select chondrosarcoma patients for treatment by the FDA-approved cMET inhibitors such as crizotinib." (PMID 36622753, 2023). "In contrast, we observed the inhibition of SULF1 expression through histone 3 K27 trimethylation by EZH2 to attenuate the elimination of 6-O-sulfation in chondrosarcoma, resulting in the high level of 6-O-sulfation of HSPGs to enhance RTK signaling like cMET." (PMID 36622753, 2023). "The regulation of EZH2/SULF1/cMET axis were further validated in patient samples with chondrosarcoma." (PMID 36622753, 2023). "The interaction between cMET and CD44 was clearly detected by immunoprecipitation analysis in vector control chondrosarcoma cell lines as reported, yet such interaction between cMET and CD44 was abolished in SULF1 overexpressed chondrosarcoma cell lines." (PMID 36622753, 2023). "q-ChIP experiments further validated enrichment of EZH2 bound at Sulf1 promoter in various chondrosarcoma cell lines." (PMID 36622753, 2023). "The expression of SULF1 in chondrosarcoma cell lines treated with EPZ-6438 (tazemetostat), an EZH2 inhibitor which reduced the enzymatical activity of EZH2 without affecting its expression, was explored by western blotting." (PMID 36622753, 2023). "Here, we identify a signal pathway way involving EZH2/SULF1/cMET axis that contributes to malignancy of chondrosarcoma and provides a potential therapeutic option for the disease." (PMID 36622753, 2023).
chondrosarcoma (continued). "In this study, we integrated EZH2-chromatin immunoprecipitation (ChIP) sequence and cDNA microarray analysis then validated in multiple chondrosarcoma cell lines to identify SULF1 as a top EZH2-targeted gene governing chondrosarcoma progression." (PMID 36622753, 2023). "The phosphorylation of cMET was dampened in SULF1 overexpressed chondrosarcoma cell lines." (PMID 36622753, 2023). "Pathological relevance of EZH2/SULF1/cMET axis in chondrosarcoma." (PMID 36622753, 2023). "(D) A propose model of the regulation of EZH2/SULF1/cMET axis in chondrosarcoma." (PMID 36622753, 2023). "Nevertheless, the role of SULF1 in chondrosarcoma is unclear." (PMID 36622753, 2023). "The results indicated that SULF1 is the direct targeted gene of EZH2 in chondrosarcoma cell lines." (PMID 36622753, 2023). "Ectopic expressed SULF1 attenuates tumorigenicity of chondrosarcoma." (PMID 36622753, 2023). "Together, these results indicated that downregulation of SULF1 enhances the complex formation of cMET, HGF, and CD44, consequently to increase the downstream survival signaling to promote tumorigenesis of chondrosarcoma." (PMID 36622753, 2023). "In chondrosarcoma, the expression of EZH2 was upregulated and thereby inhibited the SULF1 expression." (PMID 36622753, 2023). "All these results revealed that SULF1 is a downstream target of EZH2 and serves as a tumor suppressor role in chondrosarcoma development." (PMID 36622753, 2023). "Simultaneously, they also showed that expression of SULF1 did not exhibit significant difference between benign tumor and distinct histological grade of chondrosarcoma." (PMID 36622753, 2023). "SULF1 is the downstream targeted of EZH2 and repressed in chondrosarcoma cell lines." (PMID 36622753, 2023). "In contrast, CA mutant SULF1 which lost enzymatic activity failed to do so in chondrosarcoma cell line." (PMID 36622753, 2023).
malignant mesothelioma (3 papers, 2012 to 2022). A malignant neoplasm of the pleura or peritoneum, arising from mesothelial cells. "SULF-1 is downregulated in many tumor types, whereas in malignant mesothelioma and some other tumors it is overexpressed." (PMID 24392351, 2013). "The massive downregulation of SULF-1 after syndecan-1 overexpression in malignant mesothelioma may constitute one mechanism by which syndecan-1 regulates cell growth, by modulating the growth factor binding properties of HSPGs." (PMID 24392351, 2013). "However, in malignant mesothelioma and a wide range of other tumors SULF1 is clearly overexpressed." (PMID 23144729, 2012).
multiple myeloma (3 papers, 2007 to 2013). "Such as the disease related target pair, hsa-miR-19b and SULF1, is beneficial for the further discovery and clinical treatment of multiple myeloma." (PMID 23467572, 2013).
osteoarthritis (3 papers, 2008 to 2023). A noninflammatory degenerative joint disease occurring chiefly in older persons, characterized by degeneration of the articular cartilage, hypertrophy of bone at the margins and changes in the synovial membrane. "In the present study, chondrocytes stimulated with IL-1β exhibited downregulation of COL2A1 and upregulation of MMP13, Prg4, Sulf1, Adam10, and Fstl1, supporting that enhanced inflammation is a critical mechanism underlying the progression of osteoarthritis." (PMID 37525533, 2023). "Sulf-1 and Sulf-2 expressions in human articular cartilage from normal donors and patients with osteoarthritis (OA) and in normal and aged mouse joints were analyzed by real-time polymerase chain reaction, immunohistochemistry, and Western blotting." (PMID 18507859, 2008). "Mice lacking the Sulf1 protein exhibit spontaneous cartilage degeneration and osteoarthritis." (PMID 37525533, 2023).
pancreatic adenocarcinoma (3 papers, 2007 to 2015). "Increased expression of Sulf1 and Sulf2 in some cancers, including pancreatic adenocarcinomas and non-small cell lung cancers is associated with overactive Wnt signalling." (PMID 25681501, 2015). "To determine if Sulf proteins were expressed by pancreatic adenocarcinoma in surgical specimens, we stained sections from seven archived cases with Sulf-1 and Sulf-2 antibodies and an IgG control." (PMID 17460759, 2007).
urothelial carcinoma (3 papers, 2017 to 2022). A malignant neoplasm derived from the transitional epithelium of the urinary tract (urinary bladder, ureter, urethra, or renal pelvis). "In contrast, increased SULF1 expression is observed in a wide range of human tumors and high SULF1 expression is associated with advanced primary tumor status, higher histological grade, and worse survival in urothelial carcinoma." (PMID 36428645, 2022). "The findings prompt us to further characterize the significance of SULF1 transcript and protein expression in our large cohort of urothelial carcinoma." (PMID 28525382, 2017). "SULF1 (human sulfatase 1) is overexpressed in GC and the inhibition of SULF1 expression resulted in decreased proliferation, migration, and invasion in urothelial carcinomas cell lines." (PMID 35328635, 2022).
acute myeloid leukemia (2 papers, 2011 to 2012). Acute myeloid leukemia (AML) is a group of neoplasms arising from precursor cells committed to the myeloid cell-line differentiation. "We observed that, in addition to previous observations, SULF1 gene expression was increased in T prolymphocytic leukemia, acute myeloid leukemia and in renal carcinoma compared to corresponding normal tissues." (PMID 21599997, 2011).
adenoma (2 papers, 2015 to 2018). A neoplasm arising from the epithelium. "The last ECM component that was significantly differentially expressed between adenoma and carcinoma is sulfatase, SULF1." (PMID 30175151, 2018). "No significant gene expression alterations could be detected in the stromal cells isolated from adenomas compared to the normals, but COL1A2, FADS1, MAL, PRIMA1, SULF1, THBS2, TIMP1 genes’ transcripts showed significant differences (p < 0.05) in logFc values for the tumour versus normal comparison." (PMID 26482433, 2015). "In addition, ALDH1A3, COL1A2, FADS1, SFRP2, SULF1, and THBS2 were found to be significantly (p < 0.01) differentially expressed in tumour samples but not in adenomas compared to healthy samples." (PMID 26482433, 2015).
breast tumor (2 papers, 2025). "Short SULF1 splice variants were predominant in breast tumors, promoting the growth of MDA‐MB231 and MCF7 cell lines derived from breast tumors induced by Fgf2 in vitro." (PMID 38590118, 2025). "SULF1 mRNA exhibited a significant increase in breast tumor tissue." (PMID 41373732, 2025).
diabetic nephropathy (2 papers, 2021 to 2024). "In addition, a recent study reported critical roles for SULF1 and SULF2 in the maintenance of glomerular integrity and their protective roles in diabetic nephropathy." (PMID 33540508, 2021).
Dupuytren disease (2 papers, 2016 to 2021). "The six Wnt-related genes that were found to be associated with Dupuytren’s disease in the GWAS were analyzed in eight (SULF1: seven) affected cords and nodules and in unaffected TLPA by performing real-time qPCR." (PMID 26635199, 2016).
esophageal squamous cell carcinoma (2 papers, 2014 to 2022). Esophageal squamous cell carcinoma (ESCC) is a type of esophageal carcinoma (EC) that can affect any part of the esophagus, but is usually located in the upper or middle third. "IGFBP7 signaling are often associated with cell growth suppression, and elevated expression of SULF1 has also been shown to inhibit HBEGF-dependent co-receptor functions of cell surface heparan sulfate proteoglycans (HSPGs) in hepatic and esophageal squamous cell cancer cells." (PMID 24690739, 2014).
head and neck carcinoma (2 papers, 2020 to 2026). A carcinoma that arises from the head and neck region. "Previous reports explored SULF1 expression mostly in cancer cells, with the majority showing reduced levels of SULF1 in progressive ovarian, hepatocellular, breast, and head and neck carcinomas." (PMID 32413029, 2020).
liver cancer (2 papers, 2016 to 2022). An epithelial or non-epithelial malignant neoplasm that arises from the liver. "Widespread low expression of the SULF1 transcript is observed in cancer cell lines and prior studies suggested a tumor suppressor function of SULF1 in ovarian, breast, and liver cancers." (PMID 36428645, 2022). "This functional relationship between Sulf-1 and Msln could be exploited for the development of a novel liver cancer therapy." (PMID 27626699, 2016).
mesomelia-synostoses syndrome (2 papers, 2014 to 2024). "8q13 has also reportedly been associated with Mesomelia-Synostoses syndrome (MSS, OMIM 600383) due to the co-deletion of SULF1 and SLCO5A1." (PMID 25135225, 2014).
mesothelioma (2 papers, 2012 to 2022). A usually malignant and aggressive neoplasm of the mesothelium which is often associated with exposure to asbestos. "Our findings seem to fit in this hypothesis: in mesothelioma cells the massive downregulation of SULF1 correlates with a growth inhibition." (PMID 23144729, 2012). "Pleural effusions from mesothelioma patients had significantly higher levels of prosaposin and SULF-1 than those from non-malignant disease patients." (PMID 36359323, 2022). "In conclusion, prosaposin and SULF-1 levels determined in pleural effusion may be promising biomarkers for differential diagnosis between mesothelioma and non-malignant pleural disease." (PMID 36359323, 2022).
schizophrenia (2 papers, 2026). A major psychotic disorder characterized by abnormalities in the perception or expression of reality. "Given that the NAc is tightly associated with psychiatric disorders, including schizophrenia, depression, and drug addiction, it may also be intriguing to study the possible contribution of Sulf1 to psychiatric disorders." (PMID 41486756, 2026).
Achalasia (1 paper, 2022). A disorder of esophageal motility characterized by the inability of the lower esophageal sphincter to relax during swallowing and by inadequate or lacking peristalsis in the lower half of the body of the esophagus. "Our study provides, for the first time, functional evidence about the PRKG1 gene as a direct target and SULF1 and SYDE1 as potential indirect substrates of miR-200c-3p and suggests the involvement of NO/cGMP/PKG signaling in the pathogenesis of achalasia." (PMID 36614110, 2022).
actinic keratosis (1 paper, 2023). A precancerous lesion of the skin composed of atypical keratinocytes. "Five new genes, HEPHL1, FBN2, SULF1, SULF2, and TCN1, were recently discovered in cSCC, which were significantly upregulated compared to normal skin (p < 0.001) and actinic keratosis (AK) (p < 0.01)." (PMID 36980718, 2023).
Anxiety (1 paper, 2021). Intense feelings of nervousness, tension, or panic often arise in response to interpersonal stresses. "Thus, Sulf1 may be associated with the functions of these groups of cells in stress, anxiety, and drug-seeking activity." (PMID 34489650, 2021).
atherosclerosis (1 paper, 2022). A disease characterized by the build-up of fatty material and calcium deposition in the arterial wall resulting in partial or complete occlusion of the arterial lumen. "Characterisation of Sulf1/Sulf2 functional heterogeneity has clinical implications not only in angiogenic cell signalling but also in the prevention or reduction of thrombosis and atherosclerosis, which requires further studies." (PMID 35409127, 2022).
bipolar disorder (1 paper, 2014). A disorder of the brain that causes unusual shifts in mood, energy, activity levels and the ability to carry out day-to-day tasks. "SULF1 is necessary for sprouting of neurite, and is involved in neurological disorder, ischemic stroke and bipolar disorder." (PMID 25559034, 2014).
bone cancer (1 paper, 2023). A primary or metastatic malignant neoplasm affecting the bone or articular cartilage. "Together, our data demonstrate that EZH2-mediated downregulation of SULF1 is critical for de-suppressed cMET signaling pathway in bone cancer." (PMID 36622753, 2023). "To further validate our observation in clinical setting, we examined the clinical significance of EZH2, SULF1, and phospho-cMET by analyzing H-score of immunohistochemistry (IHC) on commercially available human bone cancer tissue array." (PMID 36622753, 2023).
disc degeneration (1 paper, 2024). "However, SULF1 was previously studied in a single global in vivo knockout model of disc degeneration, and its specific role in CEP cells has not been fully ascertained." (PMID 38173036, 2024).
endothelial dysfunction (1 paper, 2024). In vascular diseases, endothelial dysfunction is a systemic pathological state of the endothelium (the inner lining of blood vessels) and can be broadly defined as an imbalance between vasodilating and vasoconstricting substances produced by (or acting on) the endothelium. "We also found dysregulation of angiogenesis genes (XDH, SEMA5A, and SULF1) and the Rap1 pathway (ADORA2B, GNAO1, SULF1, and EFNA2), which promotes endothelial homeostasis and may be involved in endothelial dysfunction-associated cardiovascular pathologies." (PMID 38255763, 2024).
epilepsy (1 paper, 2020). A brain disorder characterized by episodes of abnormally increased neuronal discharge resulting in transient episodes of sensory or motor neurological dysfunction, or psychic dysfunction. "Thus, L2–3_Cux2 and L5–6_Fezf2 subtypes co-clustered with Sst_Tac1 and Vip_Cbln1 subtypes, whereas L3_Cux2_Prss12 co-clustered with Pvalb_Sulf1, which might underlie local neuronal networks with most strongly affected in the epilepsy transcriptome." (PMID 33028830, 2020).
gallbladder carcinoma (1 paper, 2020). "Inhibition of human sulfatase 1 (SULF1) inhibits the malignant phenotype of gallbladder carcinoma cells by hindering the cell response to growth factors." (PMID 32916872, 2020).